CGAS (cyclic GMP-AMP synthase)
Diseases named in the same sentence as CGAS in open-access papers (continued):
Sharing a sentence is not in itself a finding about the gene and the disease.
infection (continued). "The cyclic GMP-AMP synthase-stimulator of interferon genes signal transduction pathway is critical in innate immunity, infection, and inflammation." (PMID 36545321, 2022). "A lung-on-chip model revealed that, in addition to macrophages, infection with SARS-CoV-2 activates cGAS–STING signalling in endothelial cells through mitochondrial DNA release, which leads to cell death and type I IFN production." (PMID 35045565, 2022). "Upon infection of DNA virus, cGAMP produced by the activated cGAS first activates STING by promoting STING translocation from the ER to the Golgi." (PMID 35803579, 2022). "Increases in cellular cGAMP levels, consistent with physiologic mitochondrial stress activation, were observed starting at 16 h after SARS-CoV-2 infection of either A549-ACE2 or Calu-3 cells, further indicating cGAS activation during infection." (PMID 35022513, 2022). "cGAS is an important innate immune sensor in most cells in response to infection of DNA pathogens and aberrant located cellular DNA." (PMID 35973990, 2022). "Since both DNA and RNA sensors trigger IRF3‐mediated type‐I IFN signaling, we considered why the MDA5/MAVS‐deficient, or cGAS/STING‐deficient, mice responded to N67C infections differently." (PMID 35635376, 2022). "It has also been suggested that infection of Japanese medaka with the intracellular bacteria, E. tarda promotes increased cGAS gene expression in the intestinal tract." (PMID 35619707, 2022). "Surprisingly, in addition to the pivotal DNA sensing mechanism mediated by cGAS-STING pathway, infection of the DNA virus ASFV activates genes associated with RNA virus response, with stronger induction by HuB20 infection." (PMID 36544767, 2022). "Using the dual RNAseq bioinformatic analyses, we found that ΔM062R infection in differentiated THP-1 cells stimulated proinflammatory state with activation of the cGAS pathway." (PMID 36103568, 2022). "The activation of cGAS-STING signaling pathway has been observed during the infection of a variety of RNA viruses, and studies have shown that the activation of cGAS-STING signaling pathway is related to the release of mtDNA caused by RNA virus infection." (PMID 36590405, 2022). "Flow cytometry analysis revealed significantly higher levels of infection in cGAS‐KO cells compared to WT and MAVS‐KO cells at both time points." (PMID 35670106, 2022). "Among them, the cGAS-STING pathway plays an important role in innate immune response to pathogen infection." (PMID 36569928, 2022). "Several other antiviral proteins, including RIG-I, MDA5, OAS, RNase L, Trim5, ADAR1, ZAP, cGAS and RNA helicases, can be recruited to SGs during infection, suggesting that these are antiviral SGs (avSGs) with a role in antiviral signalling." (PMID 35098996, 2022). "The cGAS-STING-mediated IFN-β signaling pathway is significantly suppressed upon the virulent ASFV Armenia/07 infection, but the viral proteins involved remain elusive." (PMID 35412346, 2022). "We also demonstrated that both the cytosolic dsRNA-sensing pathway mediated by MDA5 and the cytosolic DNA-sensing pathway mediated by cGAS/STING have important functions in host defense against VACV∆C7L infection." (PMID 35351885, 2022). "Meanwhile, cGAS is critical for the induction of type I IFN response to infection by various bacteria such as Chlamydia trachomatis, Mycobacterium tuberculosis, Listeria monocytogenes, and Neisseria gonorrhoeae." (PMID 35536585, 2022). "Upon infection-mediated activation of cGAS, the synthesized cGAMP binds to STING, which interacts with SEC24C and buds out of the ER into coat protein complex II vesicles to form the ERGIC." (PMID 35536585, 2022). "Another recent study demonstrated that the attenuated NH/P68 strain activated the cGAS-STING-IRF3 signaling cascade early during infection, thus enhancing IFN-β expression in infected Mφ, compared to the virulent Armenia/07 strain." (PMID 35215119, 2022).
infection (continued). "The antiviral role for cGAS at a later time point coincides with the timeframe required for cell-to-cell fusion, which occurs around 12–14 h post infection." (PMID 34732709, 2021). "Listeria monocytogenes, a Gram-positive bacterium replicating in myeloid cells, induced IFNβ expression through both IFI16 and cGAS detection upon infection." (PMID 33708225, 2021). "The cyclic GMP‒AMP (cGAMP) synthase (cGAS) is a cytosolic DNA sensor that plays a vital role in innate immune defense against pathogen infection or damage-induced host DNA aberrantly localized in the cytosol." (PMID 34665236, 2021). "The cyclic GMP-AMP (cGAMP) synthase (cGAS) was most strongly 98-fold upregulated upon infection, acting as sensor of viral RNA." (PMID 34777295, 2021). "In summary, immunotherapy targeting the cGAS-STING signaling pathway to treat AMR infections is a reliable line of research." (PMID 35095914, 2021). "Because R. equi is thought to be confined by a phagosomal membrane until 24h post-infection in macrophages, it was puzzling to observe activation of the cytosolic DNA sensor cGAS early during infection that also required bacterial de novo protein synthesis." (PMID 34473814, 2021). "Functions of the cytoplasmic DNA sensor, cyclic GMP-AMP synthase (cGAS) during the infection of several DNA viruses have been exclusively investigated." (PMID 34987495, 2021). "Infection with the bacterial pathogen such as mycobacterium tuberculosis can trigger cGAS and then stimulate IRF3-dependent type I interferon response." (PMID 34016129, 2021). "Similar to the other two herpesvirus subfamilies, the cGAS-STING pathway targets KSHV upon infection." (PMID 34440891, 2021). "At 24 h post infection, cGAS depletion led to significantly elevated viral replication, indicating that cGAS-mediated signaling is required for optimal host defense against SARS-CoV-2." (PMID 34732709, 2021). "In the present study, we found that PCV2 infection phosphorylates cGAS at S278 site via Cap binding protein gC1qR-mediated Akt signaling activation, which directly silences the catalytic activity of cGAS in the early phase of infection." (PMID 34543359, 2021). "Most studies examining the role of IRF1 in pathogen defense suggest it is an inducible factor, triggered by infection and contributing to the activation of innate immune responses induced by pathogen sensors such as RLRs, TLRs, or cGAS." (PMID 33476326, 2021). "Our work adds to the list of HCMV factors that inactivate the cGAS/STING/TBK1 pathway during productive infections of highly differentiated cells and initiates the list of those that do so during latency within incompletely differentiated myeloid cells." (PMID 34903048, 2021). "During the parallel evolution between host cells and M. tuberculosis, M. tuberculosis has developed many strategies to evade the surveillance of the cGAS-STING pathway to establish infection." (PMID 35095914, 2021). "The presence of dsDNA in the cytosol is a strong damage signal that indicates infection or corruption of the mitochondria or nucleus. dsDNA is sensed by cyclic GMP-AMP synthase (cGAS), which catalyses the formation of cGAMP, a cyclic dinucleotide." (PMID 33731858, 2021). "For example, herpes simplex virus 1 (HSV-1) is detected in human fibroblasts by cGAS early during infection, while both RIG-I and cGAS equally contribute to innate sensing of HSV-1 late during infection." (PMID 33849980, 2021). "Specifically, the cytosolic DNA sensor, cGAS is activated by binding bacterial DNA during infection with M. tuberculosis, F. novicida, Legionella pneumophila and Chlamydia spp." (PMID 34473814, 2021). "Infection of macrophages revealed a STING-dependent activation of antimicrobial response following direct binding of cytosolic DNA to cGAS, leading to an autophagy-driven elimination of M. tuberculosis." (PMID 33708225, 2021).
infection (continued). "In particular, the cGAS/STING/TBK1 foreign DNA sensing pathway is a major contributor to the IFN response during infection with DNA viruses." (PMID 34903048, 2021). "For example, the dengue virus protein NS2B promoting cGAS degradation in autophagy–lysosome-dependent manner results in inhibition of IFN-I production during infection." (PMID 34394047, 2021). "In line with this, cyclic dinucleotide 2′3′-cGAMP, a molecule produced by activated cGAS, was significantly increased after 16 h of infection." (PMID 34732709, 2021). "This study reveals that PCV2 can inhibit the activation of cGAS signaling pathway through two different mechanisms at different stages of infection and clarifies the internal relationship and cooperation model between these two mechanisms." (PMID 34543359, 2021). "In the cells infected with a lower multiplicity of PCV2, ubiquitinated cGAS proteins were gradually accumulated with the prolonged infection times in the presence of autolysosome inhibitor bafilomycin A1 (Baf)." (PMID 34543359, 2021). "Upon infection with R. equi, cGAS KO macrophages had reduced levels of Ifnb, Isg15 and Ifit1 transcripts, and a significant but less dramatic reduction in Tnfa." (PMID 34473814, 2021). "The functional conservation of the cGAS-STING pathway during evolution highlights its importance in host cellular surveillance against pathogen infections." (PMID 33708225, 2021). "Release of Mn into the cytosol during infection with dsDNA viruses increases activation of the cGAS-STING pathway by elevating production of cGAMP that stimulates NFκB-dependent expression of the anti-viral interferon response." (PMID 33493177, 2021). "The transcript levels of DNA sensors Aim2, cGas, and Sting were also significantly elevated in the Nlrp3−/− mice on day 7 post-infection than those observed for F. tularensis LVS-infected wild-type mice." (PMID 34690967, 2021). "In summary, the data presented in this work demonstrate that PCV2 infection promotes the infection various DNA viruses through targeting porcine cGAS to inhibit IFN-β induction relying on followed mechanisms." (PMID 34543359, 2021). "Given the ongoing interplay between HPV and antiviral responses, we postulate that evasion of cGAS/STING responses during initial infection would be beneficial to the viral lifecycle." (PMID 33253291, 2020). "Here, we directly compare human keratinocyte cGAS/STING responses to HPV virion infection versus responses to cationic lipid transfection of dsDNA plasmid." (PMID 33253291, 2020). "Here, by using virus genetics in ECTV and the infection of its natural host, we reveal the enormous contribution of the cGAS-STING pathway in conferring protection against lethal poxvirus infection." (PMID 32948585, 2020). "Cellular sensing of initial HPV infection has not been formally investigated, but several studies have described roles for the early HPV oncogenes in antagonizing the cGAS/STING/IRF3 axis following establishment of infection." (PMID 33253291, 2020). "Unleashed cGAS-STING activation during ECTVΔvSlfn infection resulted in strong inflammation in the inoculation site that correlated with a prominent IFN-I signature in the lymph node and the spleen." (PMID 32948585, 2020). "Mirroring the role of cyclic GMP-AMP synthase (cGAS) in eukaryotic defence against viruses as part of the cGAS-STING pathway, bacterial cGAS enzymes have recently been discovered that abort infection by activating phospholipases through cGAMP signaling." (PMID 32338598, 2020). "The cGAS-STING system was also shown to sense MVA DNA in the cytoplasm of conventional DCs during infection." (PMID 33092186, 2020). "Cyclic GMP-AMP synthase (cGAS) is a cytosolic DNA sensor and was originally found to sense pathogen DNA during infection." (PMID 32541866, 2020).
infection (continued). "To elucidate the nature of the protective host response elicited after activation of the cGAS-STING axis upon ECTV∆vSlfn infection, we carried out transcriptomic analysis [RNA sequencing (RNA-seq)] from relevant infected tissues." (PMID 32948585, 2020). "For example, cGAS−/− mice displayed enhanced rates of infection and mortality when compared with wild type mice, which was infected with the +ssRNA West Nile virus." (PMID 31940818, 2020). "The induction of IFN-I in response to infection is primarily mediated by Cyclic GMP-AMP synthase (cGAS)-Stimulator of interferon genes (STING) pathway." (PMID 32477956, 2020). "We next tested the complete cGAS/STING pathway using infection with MVA-gfp, or transfection with HT-DNA and with HBV nucleic acids from viral particles." (PMID 32485908, 2020). "This raises the possibility that cyclic di-nucleotides produced by L.m. accumulate to generate cGAS-independence of STING activation at delayed stages of infection." (PMID 33178195, 2020). "(H) Percentage infection of control, cGAS-/-or MAVS-/- THP-1 knock out cells infected with HIV-GFP at indicated doses of RT (SG-PERT)." (PMID 33300875, 2020). "Various proteins indicating infection enhance the interaction between DNA and cGAS, thus lowering the DNA detection threshold and increasing the sensitivity of cGAS." (PMID 32532954, 2020). "A recent study found that glutamylation and deglutamylation of cGAS modulates immune responses to infection with DNA viruses, evidenced by the fact that Ccp5−/− or Ccp6−/− mice are more susceptible to DNA virus infection." (PMID 33105828, 2020). "The cGAS-STING pathway can mediate protective immune defense toward infection with a great number of DNA-containing pathogens, as well as generate intrinsic antitumor immunity." (PMID 33006365, 2020). "Sensors such as RLRs, ALRs, and cGAS are responsible for the innate immune response to cytosolic and nuclear nucleic acids produced upon infection or in actively infected cells." (PMID 32751803, 2020). "Infection in the presence of the capsid destabilising small molecule PF‐74 also induced a cGAS‐dependent IFN response." (PMID 32852081, 2020). "If this effect of Vpr is relevant to infection, we expect that cGAS/STING activated by the incoming HIV genome should be sensitive to the amount of Vpr contained in an individual particle." (PMID 33300875, 2020). "The cGAS-STING pathway is a major sensor of pathogen infection in mammalian cells where it functions to detect mislocalized cytosolic DNA exposed during infection." (PMID 33191912, 2020). "Whereas self-DNA normally resides in the nucleus and is thus largely immune from detection, foreign DNA residing in the cytosol upon pathogen infection or micronucleus envelope disruption can be recognized by cyclic GMP-AMP synthase (cGAS)." (PMID 33230251, 2020). "Next, we validated the interaction of CHIKV 181/25 nsP4 with cGAS in the context of infection by over-expression of cGAS in HEK-293T for 24 hrs followed by infection with CHIKV 181/25 and subsequent cGAS immunoprecipitation." (PMID 33057424, 2020). "This functional mechanism of mammalian cGAS was also confirmed by infection with intracellular bacteria and parasites." (PMID 33023222, 2020). "STING also plays a central role in detection of DNA from bacteria and infection-induced host cell damage by sensing 2′3′ cGAMP produced by the DNA sensor cGAS." (PMID 32153571, 2020). "This differential in vivo dependence of functional cGAS/STING to control infections was confirmed using knockout mice." (PMID 32153571, 2020). "Following the infection of DNA viruses, cytosolic ion level is enhanced in the host cells, and this increase directly induces the activity of the cGAS/STING signaling pathway." (PMID 31940818, 2020). "We further show that infection with C. acnes stimulates IFN-I production via the cGAS-STING pathway with a strong dependency on the adapter molecule TRIF." (PMID 33178195, 2020).
infection (continued). "It is now clear that the inappropriate discharge of mtDNA into the cytoplasm is recognized by the host cell as a “prokaryotic infection event” that engages the DNA sensor cGAS to promote STING-dependent signaling." (PMID 32102993, 2020). "The cGAS-STING pathway plays a central role in sensing cytosolic DNA upon infection with DNA from bacteria and DNA-viruses (including endogenous retroviruses)." (PMID 33335532, 2020). "We therefore studied the correlation between IFN-β production and cGAS-STING pathway activation in macrophages after infection with attenuated or virulent ASFV." (PMID 30918080, 2019). "In contrast, the cGAS-STING pathway is efficiently activated during NH/P68 attenuated strain infection, leading to the production of large amounts of IFN-β." (PMID 30918080, 2019). "To directly address the role for T1-IFN in control of VACV replication in vivo, we compared VACV titer in the ears of cGAS-/- and IFNαR-/- mice to wild-type mice at 5 days post-infection, the peak of VACV replication." (PMID 31603920, 2019). "Induction of T1-IFN requires infection of specialized populations of tissue-resident cells that can subvert the viral blockade of cGAS/STING sensing." (PMID 31603920, 2019). "A recent study demonstrates that DENV NS2B targets the DNA sensor cyclic GMP-AMP synthase (cGAS) for lysosomal degradation to avoid the detection of mtDNA during infection." (PMID 31531178, 2019). "We have observed that infection with NH/P68 is able to substantially activate the cGAS-STING pathway." (PMID 30918080, 2019). "The expression profile of Ips-1 was initially suppressed up until 5 h post-infection followed by an activation, while cGas exhibited an early activation between 1 and 3 h post-infection, followed by a rapid drop in expression." (PMID 30886604, 2019). "cGAS-/- mice displayed increased tissue thickness beginning by 3 days post-infection, the time point at which we first measured induction of T1-IFN transcripts." (PMID 31603920, 2019). "One recent report indicated that, in addition to being activated by infection with DNA viruses, the cGAS-cGAMP-STING axis is also activated by infection with RNA viruses." (PMID 31616416, 2019). "Our research group reported that the IFN pathway was activated upon FHV-1 infection through the cGAS pathway at early infection but was soon blocked by multi-ORFs of FHV-1." (PMID 31861450, 2019). "In recent reports, cyclic GMP-AMP synthase (cGAS) has been identified as a key cytosolic DNA sensor and participant in many innate immune responses, particularly in antiviral, anti-infection, and immunologic adjuvants." (PMID 30791397, 2019). "We found that the cGAS pathway was activated and promoted the expression of related signaling proteins during infection." (PMID 30791397, 2019). "Similar to the results obtained in cells depleted for STING, MVA infection triggered a significantly reduced response in cells depleted for cGAS." (PMID 29491158, 2018). "When treating cGas-/- mice, however, only the pretreated group had a 100% overall survival, while almost all the post-treated mice eventually succumbed to the infection, although the two-times post-treatment led to significantly improved survival." (PMID 29608601, 2018). "cGAS WT expression in cGAS(−) L929 cells robustly induced IFNβ mRNA production upon HSV-1ΔICP34.5 infection or HT-DNA stimulation, whereas expression of the cGAS K335R mutant led to a minimal induction of IFNβ mRNA under the same conditions." (PMID 29426904, 2018). "As compared with a low infection dose, we observed reduced progeny release (3.2-fold and 2.5-fold in Sting−/− and cGas−/− cells, respectively) at 48 hpi." (PMID 29963044, 2018). "Stinggt/gt mice had the highest levels of infection, about 2-fold higher than cGas KO/DDX41 siRNA or CD11cCre-DDX41/cGAS siRNA mice." (PMID 29871919, 2018).